WFDC2 (WAP four-disulfide core domain 2)
Diseases named in the same sentence as WFDC2 in open-access papers (continued):
Sharing a sentence is not in itself a finding about the gene and the disease.
ovarian carcinoma (continued). "A number of different expression studies have clearly identified that WFDC2 is disregulated at the RNA level in ovarian cancers and a recent study has suggested that measuring levels of WFDC2 in the serum of patients with ovarian cancer may be useful in monitoring disease progression." (PMID 16600032, 2006). "WAP four-disulfide core domain 2 (WFDC2/HE4) is an EOC clinical biomarker, and cellular retinoic acid-binding protein 2 (CRABP2) is upregulated in ovarian cancer and contributes to tumor growth and tumor cell migration and invasion." (PMID 37525249, 2023). "Both models each had two proteins (KRT19, WFDC2 and FOL1R, MUCIN-16, respectively) overlapping with our previously published 11-biomarker panel for ovarian cancer." (PMID 35406529, 2022). "The product of the HE4 gene, also known as WFDC2, is a secretory glycoprotein which primarily develops in human ovarian cancer cells with a molecular weight of about 13 KD and further converts to a N-glycosylated protein with a molecular weight of about 25 KD." (PMID 34306124, 2021). "In our study, several DEGs, including WFDC2, INAVA, and AOX1, in ovarian cancer revealed by our meta-analysis have been validated to potentially participate in ovarian cancer development and progression." (PMID 33135729, 2020). "The degree of expression of WFDC2 were significantly associated with longer survival in EC (log rank p = 0.0117).Taken together, these data strongly indicate that enhanced WFCD2 may play a role in the progression of the primary ovarian cancer cell to peritoneal metastasis." (PMID 28679402, 2017). "Another important protein biomarker for early detection of ovarian cancer is human epididymis protein 4 (HE4), a secreted glycoprotein product of the WFDC2 gene." (PMID 26779370, 2015). "HE4, also known as WFDC2, is a useful biomarker for ovarian cancer when either used alone or in combination with CA125." (PMID 23502467, 2013). "In light of the multiple reports of disregulated WFDC2 expression in ovarian cancers and the smaller number of reports that the gene may also be differentially expressed in sub-groups of pulmonary cancers we stained sections of a variety of lung carcinomas with the WFDC2 antibody." (PMID 16600032, 2006). "WFDC2 and KRT19 have previously been associated with ovarian cancer but RBFOX3 has not previously been identified as a potential biomarker." (PMID 39068297, 2024). "HE4 (Human Epididymis 4), also known as WAP four-disulfide core domain protein 2 (WFDC2), is a blood biomarker previously evaluated in the literature for ovarian cancer screening and used as an aid to surgical management decisions." (PMID 34359357, 2021). "Also known as WAP 4-disulphide core domain 2 (WFDC2), HE4 was first introduced as an ovarian cancer biomarker in 1999." (PMID 33800113, 2021). "Another ovarian cancer biomarker is human epididymis protein 4 (HE4; also known as WFDC2)." (PMID 30064416, 2018). "We previously discovered Human epididymis protein 4 (HE4, WFDC2) as a marker for ovarian cancer, first as a transcript in tissue and, four years later, as protein in serum, and identified several other genes and serum markers that similarly discriminated ovarian cancer from controls." (PMID 26565788, 2015). "Using comparative hybridization assays on an array of 21,500 ovarian cDNAs, Hood and coworkers identified the HE4 (WFDC2) gene as more highly expressed in ovarian cancer tissue than in noncancerous ovarian epithelium." (PMID 25863801, 2015). "The human epididymis protein 4 (HE4) (also called WFDC2) was originally identified as a small secreted protein that plays a role in sperm maturation in males, and it was found to be expressed in some ovarian cancers." (PMID 26552478, 2015). "In addition to MUCIN-16 and WFDC2 which are used in the ROMA-index, a number of studies have indicated that additional protein biomarkers can be informative for e.g., triaging or early diagnosis of ovarian cancer." (PMID 39068297, 2024).
ovarian carcinoma (continued). "So we could not help to speculate that WFDC2 might also play some role in the estrogen-sensitive ovarian cancers." (PMID 26928556, 2016).
endometrial cancer (82 papers, 2009 to 2026). Primary or metastatic malignant neoplasm involving the endometrium (mucous membrane that lines the endometrial cavity). "Human epididymis protein 4 (HE4), encoded by the gene WFDC2 (WAP Four-Disulfide Core Domain 2), turns out to be an important marker not only in diagnosis but also in prognosis, monitoring and as a prognostic factor in endometrial cancer." (PMID 37371799, 2023). "WFDC2 is a potential early diagnostic marker of gynecological cancers, such as ovarian and endometrial cancer." (PMID 29713252, 2018). "Further investigations into differentially expressed proteins in non-malignant and type I and II endometrial cancer samples using iTRAQ identified 1387 proteins, with 3 novel candidates suggested: WFDC2, CLU, and MUC5B." (PMID 39194522, 2024).
ovarian tumors (58 papers, 2006 to 2025). "Indeed, although the function of WFDC2 remains unresolved a number of studies have reported that WFDC2 RNA is over-expressed in ovarian tumours and in subgroups of lung adenocarcinomas." (PMID 16600032, 2006). "Besides, our functional study on WFDC2 effects on cell proliferation consolidated the previous discovery that WFDC2 gene overexpression could promote ovarian tumor growth." (PMID 33135729, 2020). "Human epididymis protein 4 (HE4), a secretory product of the WFDC2 gene, is a glycoprotein that originates from the epithelial cells of the human epididymis, which is overexpressed in ovarian tumors." (PMID 33916250, 2021).
lung carcinoma (37 papers, 2006 to 2025). "We identified 28 proteins associated with the risk of lung cancer overall and/or at least one histological subtype that included WFDC2 and CEACAM5 [1.52 (1.39–1.67) and 1.44 (1.33–1.56)]." (PMID 38750076, 2024). "The association of WFDC2 re-expression with other types of cancers has not been addressed in any great detail, although it has been shown in molecular classification studies that WFDC2 expression is associated with different subtypes of adenocarcinomas and some other lung cancer types." (PMID 16600032, 2006). "We also suggest that WFDC2 re-expression in lung carcinomas may prove to be associated with tumour type and should be studied in further detail." (PMID 16600032, 2006). "This differential expression highlights that WFDC2 has a complex role in lung cancer and its potential as a biomarker for specific cancer subtypes." (PMID 40727473, 2025). "Several studies have demonstrated that serum WFDC2 levels are valuable for the diagnosis or prognosis of lung cancer." (PMID 39296934, 2024). "First, TCGA (The Cancer Genome Atlas) databases were used to analyze whey‐acidic‐protein 4‐disulfide bond core domain 2 (WFDC2) gene expression levels in lung cancer tissues." (PMID 38742362, 2024). "Our study first used large public databases to analyze the expression of the WFDC2 gene in lung cancer tissues and then compared HE4 with classical tumor markers at the serological level." (PMID 38742362, 2024). "They found that the levels of serum WFDC2 were generally elevated in lung cancer patients, making it easy to distinguish the lung cancer patients from healthy controls." (PMID 39296934, 2024). "Analysis of the TCGA and UALCAN (The University of Alabama at Birmingham Cancer Data Analysis Portal) databases showed that WFDC2 gene expression levels were upregulated in lung cancer tissues (p < 0.01)." (PMID 38742362, 2024). "WFDC2 is upregulated in lung cancer and has thus recognized the clinical application of WFDC2 as a serum tumor marker in the early diagnosis and efficacy monitoring of lung cancer." (PMID 36245988, 2022). "In our previous study we had shown that WFDC2 was expressed in a number of lung cancer cell lines, some of which also expressed SLPI and elafin." (PMID 16600032, 2006). "This suggests a subtype-specific prognostic role of WFDC2 in lung cancer." (PMID 40727473, 2025). "This indicates that WFDC2 expression varies across different lung cancer subtypes." (PMID 40727473, 2025). "Moreover, the correlation of WFDC2 expression with lung cancer progression underscores its potential for improving diagnostic strategies and informing treatment decisions." (PMID 40727473, 2025). "This suggests that serum WFDC2 levels are a strong prognostic indicator for lung cancer patients." (PMID 39296934, 2024). "Therefore, our study first used large public databases to analyze the expression of the WFDC2 gene in lung cancer tissues and then compared HE4 with classical tumor markers at the serological level." (PMID 38742362, 2024). "All these results indicated that WFDC2 acted as a pro-oncogenic regulator in lung cancer." (PMID 35924143, 2022). "One DCB gene (WFDC2) was identified in both breast and lung cancer samples." (PMID 33883548, 2021). "Additionally, along with further exploration, researchers found that WFDC2 presented a high expression state in lung cancer and recognized that WFDC2 as a serum tumor marker had important clinical application in the early diagnosis of lung cancer and the monitoring of a curative effect." (PMID 32850406, 2020). "WFDC2 expression was higher in LUAD than in LUSC, indicating a subtype-specific pattern in lung cancer." (PMID 40727473, 2025). "Our results showed elevated levels of WFDC2 in the plasma of early-stage LUAD patients and enhanced proliferation of lung cancer cells with ectopic expression of WFDC2." (PMID 36721112, 2023).
lung carcinoma (continued). "We have also found a similar lack of induction of WFDC2 gene expression in lung cancer cell lines treated with pro-inflammatory mediators (results not shown)." (PMID 16600032, 2006). "The results of the present study showed that MDK, WFDC2, and CXCL14 were upregulated in early-stage LUAD and upregulated expressions of three secreted proteins promoted the proliferation of lung cancer cells, suggesting that these proteins might be involved in the tumorigenesis of LUAD." (PMID 36721112, 2023).
lymph node metastasis (32 papers, 2013 to 2025). "WFDC2 has also been demonstrated to be a more sensible predictor of lymph node metastasis (sensitivity of 0.82) in relation to MUC16 (0.72) and better in predicting myometrial invasion (AUC of 0.76) than MUC16 (AUC = 0.65)." (PMID 32560580, 2020).
serous ovarian cancer (28 papers, 2008 to 2025). "The expression pattern in tumour tissue of the glycosylphosphatidylinositol (GPI)-anchored placental alkaline phosphatase (ALPP) is suggested as a complementary biomarker to MUCIN-16 and WFDC2 for early detection in serous ovarian carcinoma." (PMID 35406529, 2022). "We therefore intend to proceed with evaluation of MUC16, WFDC2, MSLN and MMP7, all of which have sensitivity >30% at 98% specificity in detection of clinically apparent serous cancers, beginning with analysis of serum specimens collected months to years prior to diagnosis of serous ovarian cancers." (PMID 18612378, 2008).
breast carcinoma (25 papers, 2010 to 2025). "Generally, WFDC2 is a secretory protein that could be detected in the serum and upregulated in various cancers including ovarian, endometrial, and breast cancer." (PMID 35924143, 2022). "Additionally, there has been a recent investigation into this marker’s application in breast cancer and, based on Wfdc2 expression isolated in myoepithelial cells, we can predict that its efficacy in determining disease prognosis is more relevant for basal carcinomas than luminal." (PMID 36630696, 2022).
renal fibrosis (21 papers, 2014 to 2025). A final common manifestation of a wide variety of chronic kidney diseases characterized by glomerulosclerosis and tubulointerstitial fibrosis. "As Wfdc2 is a secretory protein associated with renal fibrosis, we chose it for further analysis in DKD patients." (PMID 37827693, 2023). "A study showed that WFDC2 circulating WFDC2 is postulated to be a biomarker of renal fibrosis in DKD patients." (PMID 33644086, 2020). "It was recently shown that WFDC2 expression in myofibroblasts from mouse kidneys mediated renal fibrosis after UUO." (PMID 26317775, 2015). "Wfdc2 may function as a protease inhibitor, which can inhibit serine protease activity and slow down the degradation of type I collagen, thereby promoting renal fibrosis." (PMID 37827693, 2023).
lung adenocarcinoma (18 papers, 2006 to 2025). A carcinoma that arises from the lung and is characterized by the presence of malignant glandular epithelial cells. "WFDC2 mRNA expression was significantly elevated in gastric cancer, lung adenocarcinoma (LUAD), esophageal carcinoma, and pancreatic ductal adenocarcinoma (p < 0.01); however, it was significantly lower in colorectal cancer (p < 0.005)." (PMID 40727473, 2025). "Similarly, in lung adenocarcinoma (LUAD), elevated WFDC2 expression has consistently been associated with better overall survival (OS), underscoring its potential as a prognostic biomarker." (PMID 40727473, 2025). "Whether WFDC2 is also an important factor affecting platinum resistance in lung adenocarcinoma needs further experimental verification." (PMID 36506331, 2022). "We have also shown that WFDC2 is expressed in the majority of cases of adenocarcinoma of the lung as well as being found in a significant number of squamous, small cell and large cell carcinomas of the lung suggesting it may have some diagnostic and/or prognostic value." (PMID 16600032, 2006).
gynecological cancers (13 papers, 2016 to 2025). "Among recently reported serum biomarkers in gynecological cancer, one of the most promising is the Human Epididymis Protein 4 (HE4 or WFDC2), a member of the whey acidic protein (WAP) four-disulfide core gene cluster bearing a conserved motif found in several protease inhibitors." (PMID 33134179, 2020).
pancreatic cancer (12 papers, 2010 to 2025). "Plasma WFDC2 levels were measured using enzyme-linked immunosorbent assay in healthy donors as well as patients with gastric, lung, colorectal, esophageal, and pancreatic cancers." (PMID 40727473, 2025). "Similarly, WFDC2 has been implicated in drug resistance and poor prognosis in pancreatic cancer, underscoring its role in cancer progression and treatment resistance." (PMID 40727473, 2025). "However, previous research from our laboratory, particularly in pancreatic cancer, has reported that high WFDC2 expression evaluated by IHC is associated with poor prognosis." (PMID 40727473, 2025). "Furthermore, our previous research demonstrated that elevated WFDC2 expression in pancreatic cancer is associated with increased tumor aggressiveness and chemotherapy resistance, with overexpression correlating with significantly shorter OS." (PMID 40727473, 2025). "WFDC2 concentrations were significantly higher in patients with gastric, lung, colorectal, esophageal, and pancreatic cancers compared to healthy donors (p < 0.01 for all comparisons, Steel test)." (PMID 40727473, 2025). "The up-regulation of WFDC2 gene has been considered an early biomarker for carcinogenesis, especially for ovarian and pancreatic cancers." (PMID 20967283, 2010). "Database analysis showed significantly elevated WFDC2 mRNA expression in several cancer types, including gastric cancer, LUAD, esophageal cancer, and pancreatic cancer." (PMID 40727473, 2025).
cystic fibrosis (11 papers, 2006 to 2025). Autosomal recessive disorder caused by pathogenic variants in the CFTR gene (cystic fibrosis transmembrane conductance regulator), which encodes a chloride and bicarbonate channel expressed in epithelial cells, and follow the diagnosis criteria. "Significant increases in the expression and localization of the WFDC2 were observed in patients with cystic fibrosis." (PMID 32337222, 2020). "It has also been reported that WFDC2 is involved in inflammatory responses and host defense, and its activity is increased in chronically inflamed lungs with cystic fibrosis." (PMID 20967283, 2010). "We used immunohistochemistry to localise WFDC2 in normal tissues of the respiratory tract, naso- and oropharynx, as well as in chronically inflamed lung from Cystic Fibrosis and a range of pulmonary carcinomas." (PMID 16600032, 2006). "Significant increases in expression and localisation of WFDC2 are seen in patients with Cystic Fibrosis." (PMID 16600032, 2006).